HAS1 (hyaluronan synthase 1)
Diseases named in the same sentence as HAS1 in open-access papers (continued):
Sharing a sentence is not in itself a finding about the gene and the disease.
melanoma (4 papers, 2016 to 2025). A malignant, usually aggressive tumor composed of atypical, neoplastic melanocytes. "In melanoma cells, a reduced amount of HAS1 positivity was associated with decreased disease-specific survival (DSS) (p = 0.013) and recurrence-free survival (RFS) (p = 0.041, data not shown)." (PMID 27184066, 2016). "A decrease in HAS1 positive melanoma cells was associated with advanced stage melanoma (p = 0.006)." (PMID 27184066, 2016). "The reduction of hyaluronan in the tumor tissue has been shown to be due to the loss of HAS1 and HAS2, and increased HYAL2, and this associated with poor prognosis and shortened disease-specific survival in melanoma." (PMID 35127523, 2021). "Decreased immunostaining intensity was observed in LN metastases compared with superficial melanomas (p = 0.013 for HAS1, p < 0.001 for HAS2)." (PMID 27184066, 2016). "Decreased intensity of HAS1 in melanoma cells was related to increased regional metastasis (p = 0.023), while decreased intensity of HAS2 was associated with distant metastasis (p = 0.004)." (PMID 27184066, 2016). "This study indicates that reduced expression of HAS1 and HAS2 is associated with melanoma progression and suggests that HAS1 and HAS2 have a prognostic significance in cutaneous melanoma." (PMID 27184066, 2016). "Furthermore, reduced HAS1 and HAS2 immunostaining in the melanoma cells was associated with increased recurrence of melanoma (p = 0.041 and p = 0.006, respectively) and shortened disease- specific survival (p = 0.013 and p = 0.001, respectively)." (PMID 27184066, 2016). "In addition, staining intensity of HAS1 in melanoma cells was decreased in LN metastases compared to deeply invasive melanomas (p = 0.018) and HAS2 intensity in melanoma cells was decreased in deeply invasive melanomas compared to superficial ones (p = 0.002)." (PMID 27184066, 2016). "Thus, the proportion of HAS1 immunopositive melanoma cells was significantly lower in LN metastases than in superficial (pT1) melanomas (p = 0.002)." (PMID 27184066, 2016). "However, the finding that HAS1 and 2 are independent prognostic factors in melanoma raises the possibility that these enzymes by themselves affect tumor progression." (PMID 27184066, 2016). "This is due to the reduced expression of HAS1 and 2 and the increased expression of HYAL2 in melanoma cells." (PMID 35127523, 2021). "Significant adverse prognostic factors for decreased DSS were increased Breslow’s depth (p = 0.001) and decreased HAS1 and HAS2 staining intensity in melanoma cells (p = 0.019 and p = 0.011, respectively)." (PMID 27184066, 2016). "Our novel data provides novel information about hyaluronan metabolism in cutaneous melanoma and points towards a significant role for HAS1 and HAS2 in melanoma dissemination." (PMID 27184066, 2016). "Similar to melanoma cells, the strongest HAS1 and HAS2 immunostaining intensity in stromal cells was observed in superficial melanomas." (PMID 27184066, 2016). "We have previously demonstrated that decreased expression of HAS1 and HAS2 and increased expression of hyaluronan degrading enzyme HYAL2 correlates with decreased tumoral hyaluronan content in the invasive melanomas." (PMID 27184066, 2016). "Here we demonstrate for the first time that decreased expression of HAS1 and HAS2 favours melanoma progression and metastasis." (PMID 27184066, 2016). "Our results demonstrate that the proportion of HAS1 and HAS2 and hyaluronan positive melanoma cells is significantly decreased in lymph node metastases, compared with superficially invasive melanoma." (PMID 27184066, 2016). "The expression of HAS1 and HAS2 was decreased in deep melanomas and metastases compared to superficial melanomas." (PMID 27184066, 2016). "The protein expression of HAS1 was not detectable in the melanoma cell lines but a strong expression was visible in epidermal melanocytes, where PACAP treatment reduced its expression." (PMID 41465475, 2025).
melanoma (continued). "Furthermore, multivariate analysis indicates that decreased expression of HAS1 and HAS2 in melanoma cells are independent prognostic factors." (PMID 27184066, 2016). "Similarly, increased distant recurrence was related to reduced HAS1 and HAS2 positive melanoma cells (p = 0.012 and p = 0.001, respectively)." (PMID 27184066, 2016). "The immunostaining of both HAS1 and HAS2 was decreased in deeply invasive melanomas and lymph node metastases compared to superficial melanomas and this associated with several known negative prognostic factors." (PMID 27184066, 2016). "Decreased tumoral hyaluronan content is accompanied by an increase in the hyaluronan degrading enzyme, hyaluronidase 2 (HYAL2), and a decrease in HAS1 and HAS2 expression in invasive melanomas and lymph node metastases compared to benign nevi and in situ melanomas." (PMID 27184066, 2016). "Our results about correlation between decreased immunostaining of HAS1 and HAS2 and decreased survival of patients support the previous works and bring us new information about histopathological changes that happen during melanoma progression." (PMID 27184066, 2016). "Furthermore, decreased HAS1 coverage in melanoma cells (p = 0.007), and decreased intensity of HAS2 in the stromal cells, was positively associated with melanoma-related death (p = 0.038; data not shown)." (PMID 27184066, 2016). "In addition to HAS1 and HAS2 expression, the observed HYAL2 expression may contribute to melanoma progression." (PMID 27184066, 2016).
Arthritis (3 papers, 2004 to 2024). Inflammation of a joint. "ANGPTL4 implicated in the chondrogenic differentiation of MSCs, whereas HAS1 has been associated with osteophyte formation and arthritis." (PMID 38200556, 2024). "The message expression of hyaluronan synthase-1 and -2 in the synovium of both types of arthritis was significantly less than in the control synovium, whereas that of hyaluronidase-2 in the synovium of both arthritides was significantly greater than in the control synovium." (PMID 15535829, 2004). "HAS is mainly divided into three subtypes: HAS1, HAS2 and HAS3, and the three subtypes are independent and differentially regulated, play a different role in arthritis." (PMID 34349767, 2021).
colitis (3 papers, 2015). Inflammation of the colon. "Our data demonstrate that both the HAS1/HAS3 double and the HAS3 null mice are protected from colitis, compared to wild-type and HAS1 null mice, as determined by measurement of weight loss, disease activity, serum IL-6 levels, histologic scoring, and immunohistochemistry." (PMID 26448758, 2015). "The HAS3 null mice have the lowest DAI, the lowest colitis score, and the lowest circulating levels of the proinflammatory cytokine IL-6, compared to the wild-type, HAS1 null, and HAS1/3 null groups." (PMID 26448758, 2015). "To test our hypothesis that HA is a key molecule that drives inflammation in the gut during intestinal inflammation, we treated mice that were null for either HAS1 or HAS3 or both HAS1/HAS3 in the experimental DSS-colitis model." (PMID 26448758, 2015). "Our data suggests that HAS1 may act as a negative regulator of HA synthesis by HAS2 since both HAS1 null and HAS1/3 double null mutants displayed higher levels of HA deposition during colitis." (PMID 26448758, 2015). "To determine whether perturbing HA production could change the course of colitis, we outbred the HAS1/3 double null mice with wild-type, background matched c57B/6 mice to generate the single HAS1 or HAS3 null strains used in the current DSS-colitis model study." (PMID 26448758, 2015). "In this study, we tested the progression of inflammation in mice null for the hyaluronan synthase genes (HAS1, HAS3, or both HAS1 and HAS3) in the DSS-colitis model." (PMID 26448758, 2015). "The HAS3 null group, similar to the HAS1/3 double null cohort, was far less affected by DSS-induced colitis." (PMID 26448758, 2015). "In the current work we found that deletion of one of the HA synthesizing enzymes, specifically HAS3, but not HAS1, significantly reduced the course of colitis in mice." (PMID 26448758, 2015). "We experimentally tested whether disrupting HA production affects the inflammation process that occurs in the murine DSS-colitis model, using HAS1 null, HAS3 null, and HAS1/HAS3 double null mice." (PMID 26448758, 2015). "HAS3 null mice exhibit decreased intestinal inflammation and tissue damage in the DSS-induced colitis model compared to wild-type, HAS1 null, and HAS1/3 double null mice while mice lacking HAS1 exhibit heightened HA deposition in both the lamina propria and submucosa during induced colitis." (PMID 26448758, 2015). "At day 10 time point, the difference is even more pronounced and demonstrates the decrease in colitis severity when the HAS3 enzyme is absent, both in the HAS3 null and the HAS1/3 null groups." (PMID 26448758, 2015).
glioma (3 papers, 2021 to 2023). A benign or malignant brain and spinal cord tumor that arises from glial cells (astrocytes, oligodendrocytes, ependymal cells). "HAS1 was observed to be significantly positively correlated with TMB in three types of tumors, namely SARC, THYM, and ACC; and significantly negatively correlated with TMB in eight types of tumors, namely GBM, glioma (GBMLGG), LGG, ESCA, stomach and esophageal carcinoma (STES), STAD, LIHC, PAAD." (PMID 37636435, 2023). "The most upregulated genes in these glioma cells were metalloproteinase (MMP)-12, MMP-9, collagen type IV, α3 (COL4-A3), and CXC-chemokine ligand 9 (CXCL9), while laminin α1 (LAMA1), integrin β2 (ITGB2), MMP-1, and hyaluronan synthase 1 (HAS1) were downregulated after Bevacizumab treatment." (PMID 36119528, 2022). "Moreover, glioma cell viability was not significantly affected when HAS2 was knocked down or HAS1 was overexpressed." (PMID 33986244, 2021). "Moreover, in view of HAS1, HAS2, and HAS3 expression in glioma, we over-expressed HAS1 and knocked down HAS2 in glioma cell lines, the results demonstrated the over-expression of HAS1 or the silencing of HAS2 did not significantly affect the viability of glioma cells." (PMID 33986244, 2021).
osteoarthritis (3 papers, 2004 to 2017). A noninflammatory degenerative joint disease occurring chiefly in older persons, characterized by degeneration of the articular cartilage, hypertrophy of bone at the margins and changes in the synovial membrane. "Has1 is upregulated in states associated with inflammation, like atherosclerosis, osteoarthritis, and infectious lung disease." (PMID 25699059, 2015). "Therefore, Has1/HAS1 up-regulation has been noted in many diseases associated with inflammation such as murine atherosclerosis, human osteoarthritis, murine infectious lung disease, and human rheumatoid arthritis." (PMID 25699059, 2015). "HAS1 expression is typically very low in healthy cells and found to be upregulated in specific inflammatory conditions like osteoarthritis." (PMID 29137675, 2017). "Interestingly, the expression of both HAS1 and HAS2 was reduced in the synovium of patients with osteoarthritis or rheumatoid arthritis compared to healthy controls." (PMID 25699059, 2015).
pancreatic cancer (3 papers, 2023 to 2025). "In pancreatic cancer, HAS1 is identified as one of the markers for iCAFs, which regulate tumor progression primarily through the secretion of growth and inflammatory factors." (PMID 40813707, 2025). "For example, three clusters had a larger contribution from pancreatic tumour/normal samples (HAS1 + CAF, metabolic CAF [meCAF] and C7 + Fib." (PMID 39757146, 2025). "High expression levels of HAS1 and HAS2 are associated with poor prognosis in various types of cancer, such as ovarian, breast, and pancreatic cancer." (PMID 37636435, 2023).
serous ovarian cancer (3 papers, 2009 to 2022). "We examined expression of HA synthases (HAS1, HAS2, and HAS3) and hyaluronidases (HYAL1, HYAL2) in primary serous ovarian cancer cells isolated from patient ascites and CBP-resistant OV-90 cells." (PMID 31443261, 2019). "We found that HAS2 and HAS3 but not HAS1 expression is significantly increased in primary serous ovarian cancer cells isolated from the ascites of patients with chemoresistant disease compared to patients with chemosensitive disease." (PMID 31443261, 2019). "In conclusion, our results indicate for the first time that decreased expression of HYAL1 rather than increased expression of HAS1–3 correlates with the accumulation of hyaluronan in serous ovarian cancer, and provides new insight in the role of hyaluronidases in human cancer in vivo." (PMID 19435493, 2009). "We additionally showed that expression of HAS2 and HAS3 but not HAS1 or hyaluronidases HYAL1 and HYAL2 were significantly increased in chemoresistant compared to chemosensitive primary serous ovarian cancer cells." (PMID 31443261, 2019).
adrenocortical carcinoma (2 papers, 2021 to 2023). "In the TCGA project, high expression of HAS1 was associated with poor overall survival (OS) in adrenocortical carcinoma (ACC), KIRP, and poor OS and DFS in GBM, KIRC." (PMID 37636435, 2023).
asthma (2 papers, 2017 to 2018). "Furthermore, it has been reported that the mRNA expression of hyaluronan synthases (HAS1 and HAS2) was upregulated in a murine model of asthma, and the production of ROS can be detected within 2 h after the stimulation of ozone on airway epithelium." (PMID 29284473, 2017).
atopic dermatitis (2 papers, 2024 to 2025). "Hyaluronan synthase subtypes HAS1 and HAS3 in RAAS exhibited distinct roles in skin biology, where HAS1 was associated with regular differentiation and repair processes, while HAS3 was linked to inflammatory responses, particularly in disorders like atopic dermatitis." (PMID 38612783, 2024).
bladder urothelial carcinoma (2 papers, 2016 to 2023). "Furthermore, increased transcription levels of HAS1 and HYAL1 are associated with metastasizing urothelial bladder carcinoma." (PMID 27184066, 2016).
colorectal cancer (2 papers, 2011 to 2020). A primary or metastatic malignant neoplasm that affects the colon or rectum. "Pathological analysis of clinical samples has demonstrated that the increased expression of HAS1 among the three HAS isoforms in human colorectal cancer tissues is correlated with lymph node metastasis." (PMID 24212952, 2011).
cutaneous melanoma (2 papers, 2016 to 2023). A primary melanoma arising from atypical melanocytes in the skin. "The present work demonstrates that reduced expression of HAS1 and HAS2 is associated with an unfavorable prognosis in cutaneous melanoma." (PMID 27184066, 2016). "Our work delivers new information about hyaluronan metabolism in cutaneous melanoma and identifies HAS1 and HAS2 as possible prognostic factors in this aggressive cancer." (PMID 27184066, 2016). "Covariates used in cutaneous melanomas (pT1 and pT4) were: Breslow’s classification, ulceration, mitotic rate, patients age and immunostaining results of HAS1 and HAS2." (PMID 27184066, 2016). "We have previously shown that synthesis of hyaluronan and expression of its synthases 1–2 (HAS1-2) decrease in cutaneous melanoma, compared to benign melanocytic lesions." (PMID 27184066, 2016). "Our previous work showed that decreased expression of hyaluronan in the cutaneous melanoma is due to decreased expression of HAS1 and HAS2 and increased expression of HYAL2." (PMID 27184066, 2016). "In the present study, we compared immunohistological staining results of HAS1 and HAS2 with clinical and histopathological parameters to investigate whether HAS1 or HAS2 has prognostic value in cutaneous melanoma." (PMID 27184066, 2016). "However, whether decreased expression of HAS1 and HAS2 is the cause or a secondary consequence of cutaneous melanoma is a question that awaits further investigation." (PMID 27184066, 2016).
endometrial cancer (2 papers, 2010 to 2011). Primary or metastatic malignant neoplasm involving the endometrium (mucous membrane that lines the endometrial cavity). "Of the 50 endometrial cancer cases, the positive immunohistochemical expression was found in 29 cases for HAS1, 33 cases for HAS2, and 29 cases for HAS3." (PMID 21904555, 2011). "We previously reported the role of HA and HAS1 in endometrial cancer." (PMID 21904555, 2011). "In our previous report and the present study, the serum levels of HA and the SHAP-HA complex were both higher in the endometrial cancer group than in the healthy control group, and the increased synthesis of HA in endometrial cancer tissue appeared to depend on the high expression of HAS1." (PMID 21904555, 2011). "In conclusion, the elevation of serum SHAP-HA complex depended on the HAS1 expression and the SHAP-HA complex is a useful marker to predict disease recurrence in endometrial cancer patients." (PMID 21904555, 2011). "The elevation of serum SHAP-HA complex depended on the HAS1 expression and the SHAP-HA complex is a useful marker to predict disease recurrence in endometrial cancer patients." (PMID 21904555, 2011).
fibrosarcoma (2 papers, 2013 to 2022). A malignant mesenchymal fibroblastic neoplasm affecting the soft tissue and bone. "We further observed that the expression of the Hyaluronan synthase 1, 2 and 3, and the Hyaluronidase 3 and 5 genes was linked to reduced life expectancy of fibrosarcoma patients." (PMID 36400790, 2022). "This is also the case in fibrosarcoma cells, as FGF-2 stimulates in a cell-specific manner the migration capability of fibrosarcoma cells by decreasing HYAL-2 expression in HT1080 cells and by increasing HAS1 and -2 expressions." (PMID 24083250, 2013). "It is also in line with the previous observation that only Hyaluronan synthase 1, but not 2 suppresses fibrosarcoma cell motility." (PMID 36400790, 2022).
head and neck squamous cell carcinoma (2 papers, 2023 to 2025). A squamous cell carcinoma that arises from any of the following anatomic sites: lip and oral cavity, nasal cavity, paranasal sinuses, pharynx, larynx, and salivary glands. "Conversely, HAS1 was significantly upregulated in head and neck squamous cell carcinoma (HNSC) and kidney renal clear cell carcinoma (KIRC)." (PMID 37636435, 2023). "To further characterized the subset of cells expressing HAS1 in human OSCC, we analyzed the correlation between HAS1 and differentially expressed genes across various tumor-associated cell populations in head and neck squamous cell carcinoma (HNSCC, n = 522, TCGA dataset, Firehose Legacy)." (PMID 40813707, 2025).
keloid (2 papers, 2018 to 2019). An irregularly shaped, elevated mark on the skin caused by deposits of excessive amounts of collagen during wound healing. "The baseline keloid model comprising the entire keloid showed no increase in epidermal thickness, but reduced COL4A2, HAS1 and MMP3 gene expression in the dermal compartment of the keloid model compared to the normal skin model." (PMID 30370495, 2018).
prostate carcinoma (2 papers, 2015). A carcinoma that arises from epithelial cells of the prostate gland. "Overexpression of HAS1 in prostate cancer was shown to be anti-tumorigenic; however, overexpression of both HAS1 and Hyal-1 increased HA fragmentation that in turn promoted tumor cell proliferation and metastasis." (PMID 26029216, 2015).
rheumatoid arthritis (2 papers, 2004 to 2015). A chronic, systemic autoimmune disorder characterized by inflammation in the synovial membranes and articular surfaces. "However, IL-1β is not able to stimulate Has1 expression in healthy synoviocytes like in type-B synoviocytes isolated from rheumatoid arthritis patients." (PMID 25699059, 2015).
Stroke (2 papers, 2024 to 2025). Sudden impairment of blood flow to a part of the brain due to occlusion or rupture of an artery to the brain. "Elevated HAS1, HAS2, HYAL1, and HYAL2 were also found in post-mortem brain tissue of stroke patients, and elevated HYAL1 was observed in serum from stroke patients." (PMID 41586378, 2025).